PTPRZ1 (protein tyrosine phosphatase receptor type Z1)
Diseases named in the same sentence as PTPRZ1 in open-access papers (continued):
Sharing a sentence is not in itself a finding about the gene and the disease.
glioma (continued). "Unlike our previous study showing syndecan 1 to be the main VAR2CSA receptor in the placental syncytium, we found several interesting hits on the glioma cell lines, including syndicans, glypicans, neuropilins, decorin, versican, CSPG4, and PTPRZ1." (PMID 31466397, 2019). "Together with PTPs that impinge upon cellular contacts (DUSP26, PTPRZ1) and phospholipid signaling (MTMR4, PTEN and PTPRN2) they provide novel cues to explore and design glioma treatment options." (PMID 27586084, 2016). "Collectively, in vitro and in vivo data demonstrate a significant reduction of tumor growth upon PTPRZ1 knock-down, prompting us to address the molecular mechanisms by which PTPRZ-B impacts on glioma cell behavior." (PMID 25238264, 2014). "This analysis identified CSPG4, PTPRZ1, and BCAN as the most highly expressed and concordant ECM targets in adult gliomas, while GPC1, CSPG5, and TNR were the top concordant targets in pediatric gliomas." (PMID 40517137, 2025). "Key genes involved in glioma cell differentiation, including ASCL1 and PTPRZ1-MET, have been shown to contribute to the development of a glioma stem cell phenotype, which is thought to be the source of resistance and relapse after initial treatment with checkpoint inhibitors." (PMID 38449858, 2024). "Among pediatric CNS neoplasms, MET gene fusions have to this day exclusively been reported in the context of infantile high-grade gliomas, while a distinctive enrichment in hemispheric tumors has been observed and recurrent MET gene fusions as PTPRZ1::MET have been reported." (PMID 38902810, 2024). "PTPRZ1 expression has been higher in glioma stem cells compared to matched non-tumoral stem cells, and PTPRZ1 knockdown decreases the cell viability and tumorsphere formation of glioma stem cells." (PMID 38167429, 2024). "In line with previous reports, high PTPRZ1 expression levels are detectable in glioma tumors (data not shown) and in human xenograft-derived cells in culture." (PMID 25238264, 2014). "This approach is also supported by an older study showing that in glioma cells that were made to not express PTPRZ1, expression of only the PTPRZ-B extracellular domain is sufficient for cell migration, while the C-terminal PDZ-binding domain is required for proliferation." (PMID 37175798, 2023). "Moreover, PTPRZ1 and SOX2 were significantly overexpressed in glioma cells and could therefore be considered as useful markers to estimate the tumor cell purity in bulk glioma tissues." (PMID 34692159, 2020). "Although PTEN and PTPRZ1 are cancer modulating genes in their own right, this synthetic lethal hypothesis sheds more light on the occurrence of PTEN deletion and PTPRZ-B upregulation within glioma specimens." (PMID 29439552, 2018). "Despite this molecular link represented by the protein PTPRZ1, there is no clear evidence in TEM of a direct interaction between mature oligodendrocytes and gliomas." (PMID 38275375, 2023).
schizophrenia (14 papers, 2016 to 2026). A major psychotic disorder characterized by abnormalities in the perception or expression of reality. "In contrast, Ptprz1 overexpression is implicated in conditions like schizophrenia, where altered PNN dynamics contribute to cognitive and synaptic dysfunction." (PMID 40522224, 2025). "PTPRZ1 SNPs significantly associating with the risk to develop schizophrenia have been reported but the gene’s link with Alzheimer’s Disease thus far is based on expression levels of RPTPζ isoforms and of its ligand pleiotrophin in postmortem material." (PMID 36755664, 2022). "As a protein tyrosine phosphatase, PTPRZ1 is seen as a potential susceptibility gene for schizophrenia." (PMID 36009085, 2022). "For example, SLC17A5 (sialin) transports neurotransmitters glutamate and aspartate, and PTPRZ1, that has been associated to schizophrenia." (PMID 33119634, 2020). "PTPRZ1, linked to receptor-type tyrosine phosphatase zeta, is a potential susceptibility gene for schizophrenia and may affect working memory in mice." (PMID 39766348, 2024). "R-PTP-zeta is predominantly expressed in the central nervous system and plays a role during development and adulthood in myelination and learning and memory processes, and PTPRZ1 may be a potential schizophrenia susceptibility gene." (PMID 30487426, 2018). "Moreover, PTPRZ1 is a potential schizophrenia susceptibility gene as reported by a previous study, which may be related to the working memory deficits in mice." (PMID 33936168, 2021). "Multiple genes in these modules, including PTPRZ1 in adulthood and RP1-35C21.2 in childhood, are associated with susceptibility to schizophrenia and depression." (PMID 39472939, 2024). "Increased mRNA expression of PTPRZ1 has been reported in the amygdala and prefrontal cortex of subjects with schizophrenia." (PMID 26839720, 2016). "Together with the increased expression of PTPRZ1 in subjects with this disorder, these findings are consistent with the possibility that increased PTPRZ1 expression may contribute to deficits in synaptic plasticity in schizophrenia." (PMID 26839720, 2016). "Three schizophrenia-unique genes related to glial cell differentiation were identified: ERBB3, PTPRZ1, and SOX10." (PMID 32398742, 2020). "For example, genes involved in the neuregulin 1–ErbB4 signaling pathway, including DOCK7, EGFR, PTPRZ1 and the key regulator ERBB4,45, 46, 47 were downregulated in undifferentiated and disorganized schizophrenia, while they were upregulated in paranoid schizophrenia." (PMID 28809853, 2017). "In contrast, mice overexpressing PTPRZ1 show hippocampal LTP deficits, as well as a number of molecular, anatomical, and behavioral abnormalities reminiscent of those observed in subjects with schizophrenia." (PMID 26839720, 2016).
astrocytoma (8 papers, 2022 to 2026). "Tumors from 3 young-adult patients with IDG-mutant astrocytomas possessed a rare in-frame protein tyrosine phosphatase receptor type Z1 (PTPRZ1)-BRAF gene fusion and two class III BRAF mutations, the substitutions G464E and D594G." (PMID 41514664, 2026). "Further investigations are required to examine whether PTPRZ1-TCR-T can be applied to oligodendrogliomas and astrocytomas or other cancer entities that display elevated PTPRZ1 expression." (PMID 39893177, 2025). "Therefore, we conducted further analysis of the PTN pathway and discovered that PTPRZ1 exhibits high expression in various subclusters of astrocytoma." (PMID 39403379, 2024). "In April 2024, the National Medical Products Administration (NMPA) of China approved the use of PLB-1001 (Britinib) in patients with astrocytoma, IDH mutant who carried the PTPRZ1-MET fusion gene." (PMID 40469416, 2025).
lung carcinoma (7 papers, 2020 to 2024). "Among them, previous studies have found that PTPRZ1 is closely related to the occurrence and development of lung cancer." (PMID 39845316, 2024). "In both types of lung cancer, PTPRZ1 expression inversely correlates with overall or disease-free survival." (PMID 37175798, 2023). "In contrast, some of the low frequency fusions, CCDC6-RET in thyroid and NSCLC lung cancer, FGFR2-BICC1 in cholangiocarcinoma, PTPRZ1-MET and KIF5B-RET in non-small cell lung (NSCLC) cancer (≤5 fusions detected) did show linkage to tumour type." (PMID 35984852, 2022).
brain tumor (6 papers, 2021 to 2025). "Collectively, the results confirm that PTPRZ1 is highly expressed in malignant brain tumor cells, most abundantly in GSCs, and that AC-like cells and GSCs are primarily targeted by PTPRZ11814-1822 TCR-T cells." (PMID 39893177, 2025). "This suggests antagonism of PTPRZ1 antagonism by PTN as a possible therapeutic approach for many primary brain tumor types." (PMID 36966348, 2023). "PTPRZ1 also forms a fusion with the nearby oncogene MET in some brain tumors that have an overexpression of the fused MET41." (PMID 35338126, 2022). "Subsequently, we advanced to investigate PTPRZ1-TCR-T in experimental brain tumors." (PMID 39893177, 2025). "PTPRZ1-specific TCR-T (PTPRZ1-TCR-T) kill target cells antigen-specifically, and in murine experimental brain tumors, their combined intravenous and intracerebroventricular administration is efficacious." (PMID 39893177, 2025). "Interestingly, PTPRZ1 appeared in our SCENIC SOX regulons, and SOX transcription factors are often hyperactive in primary brain tumors." (PMID 36966348, 2023).
breast carcinoma (5 papers, 2018 to 2024). "PTPRZ1 is expressed in different types of human breast cancers, both in the breast cancer cells themselves and in carcinoma-associated fibroblasts." (PMID 37175798, 2023). "In triple-negative breast cancer, PTPRZ1 is overexpressed, as assessed by immunohistochemistry in 325 cases of breast cancer, and it may be an independent risk indicator for recurrence and metastasis." (PMID 37175798, 2023). "High PTN/PTPRZ1 expression is associated with poor chemosensitivity in breast cancer patients." (PMID 30497491, 2018). "We found that ITGB4 expression correlated with PTPRZ1 in tumor samples from patients with both invasive breast carcinoma and basal-like breast cancer." (PMID 39518121, 2024). "In breast cancer, PTPRZ1 and PTN are highly expressed in relapsed as well as chemo-resistant TNBC, and PTPRZ1 is considered as an independent risk indicator for TNBC recurrence and metastasis." (PMID 39518121, 2024). "Together, our data demonstrates the importance and critical roles of UCHL1 and PTPRZ1 in promoting the integrin α6β4-driven invasive phenotype of breast cancer cells." (PMID 39518121, 2024). "Previous studies in breast cancer highlighted that PTPRZ1 was a risk factor for poor prognosis in TNBC and found that PTN-PTPRZ1 was driven by chemotherapy, indicating its role in chemoresistance that gives rise to disease recurrence." (PMID 39518121, 2024). "Previous studies in breast cancer highlighted that PTPRZ1 is a risk factor for poor prognosis in TNBC and found that PTN-PTPRZ1 is driven by chemotherapy, indicating its role in chemoresistance." (PMID 39518121, 2024). "We also found that integrin β4 gene expression correlates with PTPRZ1 in breast cancer patient samples." (PMID 39518121, 2024). "To examine the clinical association of PTPRZ1 with integrin β4 (ITGB4) in breast cancer, we assessed the correlation of ITGB4 and PTPRZ1 by analyzing the data from the TCGA PanCancer Atlas Breast Invasive Carcinoma Dataset." (PMID 39518121, 2024). "First, we assessed the prognostic value of the expression of individual genes in the integrin α6β4-UCHL1-Hif1α-PTPRZ1 pathway on survival outcomes in breast cancer." (PMID 39518121, 2024). "PTPRZ1 protein has been detected by immunohistochemistry in the cell membrane, the cytoplasm, and the nucleus in different breast cancer cells, in line with another study showing cytoplasmic and nuclear PTPRZ1 localization in endothelial cells." (PMID 37175798, 2023). "We used the ESTIMATE algorithm to correlate the extent of stromal cells with expression of IL-34, CSF-1, CSF-1R, PTPRZ1, and syndecan-1 in breast cancer tissue from the TCGA breast cancer dataset." (PMID 29796177, 2018). "Next, we examined the prognostic effect of CSF-1, CSF-1R, PTPRZ1, and syndecan-1 expression in the breast cancer TCGA dataset by generating Kaplan–Meier survival curves split in high (top 50%) and low (bottom 50%) gene expression." (PMID 29796177, 2018). "Chemotherapy-driven increases in the CDKN1A/PTN/PTPRZ1 axis activate the NF-κB pathway in breast cancer cells." (PMID 30497491, 2018). "In this study, we uncovered that the protein levels of PTN and PTPRZ1 are significantly higher in human breast cancer tissue after receiving chemotherapy compared with cancer tissue from the same patient prior to chemotherapy." (PMID 30497491, 2018). "Together with our in vitro experiments these findings suggest that CSF-1R-independent actions of IL-34 via PTPRZ1 should be considered in evaluating IL-34 roles in breast cancer subtypes." (PMID 29796177, 2018). "In conclusion, we have demonstrated that the expression levels of PTN and PTPRZ1 were upregulated in breast cancer tissue after chemotherapy compared to tissue before chemotherapy." (PMID 30497491, 2018). "That means chemotherapy drugs may be one of the activation factors for PTN/PTPRZ1 pathway, following with an even bad chemotherapy sensitivity to these aggressive breast cancer phenotypes." (PMID 30497491, 2018).
breast carcinoma (continued). "Together with the observed low CSF-1R activation in breast cancer cells, we hypothesize that IL-34 and its receptor PTPRZ1 directly regulate cancer cells, whereas CSF-1/CSF-1R are primarily involved in regulation of stromal and immune cells." (PMID 29796177, 2018). "Although our research is the first to indicate that the therapy-induced chemoresistance of breast cancer is regulated by PTPRZ1, the mechanism behind the decreases in the other splicing variants and deglycosylated isoforms that occur during chemotherapy need further exploration." (PMID 30497491, 2018). "Thus, we analyzed potential mRNA expression differences of CSF-1, CSF-1R, PTPRZ1, and syndecan-1 between breast cancer samples and normal breast tissue samples from the TCGA breast cancer dataset." (PMID 29796177, 2018). "Whether other factors exist in breast cancer cells that affect the expression of PTPRZ1 under the treatment of Dox, we still need more evidence." (PMID 30497491, 2018). "Our studies indicated that chemotherapy-driven increases in the CDKN1A/PTN/PTPRZ1 axis play a critical role in chemoresistance, which suggests a novel strategy to enhance chemosensitivity in breast cancer cells, especially in those of the triple-negative subtype." (PMID 30497491, 2018). "Finally, public breast cancer database analyses demonstrated that ITGB4 correlates with PTPRZ1 and that high expression of ITGB4, UCHL1, HIF1A, and PTPRZ1 associated with decreased overall survival, distant metastasis free survival, post progression survival, and relapse-free survival." (PMID 39518121, 2024). "We demonstrated the tumour-promoting effects of PTN in breast cancer cells undergoing chemotherapy involved the upregulation of the expression of PTPRZ1, while the increased expression of PTPRZ1 could also stimulate the secretion of PTN to form a positive feedback loop in TNBC cells." (PMID 30497491, 2018). "Our current studies showed that the expression of PTN and its receptor PTPRZ1 in human breast cancer tissue depended on whether the patient received chemotherapy, and chemotherapy-driven increases in PTN/PTPRZ1 signalling could inhibit chemotherapy responsiveness in TNBC cells." (PMID 30497491, 2018). "In addition, we found that the Dox + PTPRZ1 group showed more obvious activation of the NF-κB pathway than PTPRZ1 group, thus demonstrating that PTPRZ1 plays an essential role in promoting the activation of the NF-κB pathway in breast cancer cells undergoing chemotherapy." (PMID 30497491, 2018). "While our study discovered a significant correlation of ITGB4 and PTPRZ1 in various cancer types, including TNBC, it is worth mentioning that ITGB4 also significantly correlated with PTPRZ1 in luminal breast cancer subtype." (PMID 39518121, 2024). "In three breast cancer cohorts, we evaluated the link between hormonotherapy response and gene expression of the two previously used brain NPC markers (DCX and PTPRZ1)." (PMID 36923306, 2022). "Since PTN and PTPRZ1 are both expressed in different subtypes of breast cancer and PTN is also found in normal breast tissues, it will be interesting to investigate how the correlation of ITGB4 and PTPRZ1 contributes to luminal cancer progression and therapeutic response." (PMID 39518121, 2024). "Using microarray data from the GEPIA database, PTPRZ1 was found significantly downregulated in breast cancer samples derived from patients that received no chemotherapy compared to samples from the normal group." (PMID 37175798, 2023). "Interestingly, ITGB4 also significantly correlated with PTPRZ1 in breast cancer Luminal A subtype, but not Luminal B or Her2 breast cancer subtypes." (PMID 39518121, 2024). "However, the cell signaling that regulates PTPRZ1 expression downstream of integrin α6β4 and how this regulation contributes to breast cancer invasive phenotype was not explored." (PMID 39518121, 2024).
breast carcinoma (continued). "We then detected the expression of PTN and PTPRZ1 in different breast cancer cell lines via RT-PCR, and we found that PTN and PTPRZ1 were expressed at higher levels in the MDA-MB-231 and MDA-MB-453 TNBC cells than the other breast cancer cells, HCC-1937 and MCF-7." (PMID 30497491, 2018).
lung adenocarcinoma (5 papers, 2022 to 2024). A carcinoma that arises from the lung and is characterized by the presence of malignant glandular epithelial cells. "However, select studies have implicated PTPRZ1 as a tumor suppressor and low PTPRZ1 expression was found to be linked to a worse response to c-Met tyrosine kinase inhibitor in lung adenocarcinoma." (PMID 39518121, 2024). "For example, PTPRZ1 is downregulated in lung adenocarcinoma but upregulated in lung squamous cell carcinoma." (PMID 37175798, 2023). "Such a discrepancy has also been found in a more recent bioinformatic analysis, showing that PTPRZ1 expression is decreased in lung adenocarcinoma but increased in lung squamous cell carcinoma." (PMID 37175798, 2023). "Finally, we have previously shown that PTPRZ1 expression is decreased in human and murine lung adenocarcinoma, in which the mTORC1 signaling pathway is activated, further supporting the importance of their potential crosstalk." (PMID 39409168, 2024). "The first study on the potential involvement of PTPRZ1 in tumor growth referred to the decreased expression of PTPRZ1 in lung adenocarcinomas compared to normal lung tissue, suggesting that PTPRZ1 may act as a tumor-suppressor." (PMID 37175798, 2023). "In contrast, several PTPs were identified as the suppressive genes in cancer, such as PTPRZ1 in BRCA and PTPRQ in lung adenocarcinoma (LUAD)." (PMID 36341348, 2022).